VDAC2 (voltage dependent anion channel 2)
Diseases named in the same sentence as VDAC2 in open-access papers (continued):
Sharing a sentence is not in itself a finding about the gene and the disease.
tumor (41 papers, 2016 to 2025). "Modulating mitochondrial outer membrane proteins, such as voltage-dependent anion channel 2 (VDAC2), offers another strategy; its loss can elicit tumor destruction while simultaneously promoting a pro-inflammatory response." (PMID 40867904, 2025). "Deletion of VDAC2 resulted in impairment of killing of tumor cells by anti-cancer agents and the ability to suppress tumor formation, similarly to the loss of BAX." (PMID 31159324, 2019). "On the other hand, high transcript levels of VDAC2 were found to be associated with increased levels of tumor recurrence and resistance to hormonal therapy in high risk breast cancer patients." (PMID 31159324, 2019). "Moreover, VDAC2 deficiency impaired chemotherapy-induced apoptosis and promoted tumor development in vivo." (PMID 40509137, 2025). "This interaction is of particular interest as VDAC2-BAK interaction helps tumor cells resist immune checkpoint inhibitors." (PMID 40911686, 2025). "As we expected, RRM2, SLC2A1, DDIT4, and VDAC2 were significantly upregulated transcriptionally and translationally in tumor samples, whereas PEBP1 and IL33 are significantly reduced in tumorous tissues." (PMID 39311766, 2024). "It is possible that Increased expression of VDAC2 induces proliferative behavior and reduces apoptosis in PAs, as observed in other neoplasms." (PMID 39449743, 2024). "Another protein located on mitochondria, voltage‐dependent anion channel 2 (VDAC2), was reported to be critical for the metabolic switch between GSCs and non‐stem tumor cells because it affects phenotype." (PMID 37576862, 2023). "The results revealed that tumours with higher TRIM21 or lower VDAC2 expression levels were infiltrated with fewer CD3+ CD8+ T cells and CD11c+ DCs, indicating weaker antitumour immunity." (PMID 36797289, 2023). "Disrupting VDAC2 expression in non‐stem tumor cells promoted the activation of glycolytic metabolism, thus potentiating the acquisition of GSC properties." (PMID 37576862, 2023). "The O-GlcNAcylation of VDAC2 is therefore a significant determinant of mitochondria survival and presumably function during major physiological processes, including tumour survival via the regulation of chemotherapy resistance." (PMID 33375613, 2020). "Does the GlcNAcylation of VDAC2 constitute a protected mitochondria phenotype, including of NK cells and other tumour microenvironment cells within such a challenging microenvironment?" (PMID 33375613, 2020). "In certain tumor cells, the tumor suppressor lipids ceramides bind VDAC2 to trigger mitochondrial apoptosis." (PMID 34766113, 2020). "Deleting VDAC2 phenocopied the loss of BAX in impairing both the killing of tumor cells by anti-cancer agents and the ability to suppress tumor formation." (PMID 30478310, 2018). "Because the enhanced in vivo tumor propagation capacity is the most important feature of GSCs that differs from NSTCs45,46, we investigated the effect of VDAC2 disruption on the ability of NSTCs to form xenografts in vivo." (PMID 30250190, 2018). "Deletion of VDAC3 significantly increases cell resistance to anti-tumor agent Erastin, which targets VDAC2 and VDAC3." (PMID 29854282, 2018). "Tumor spheroids exhibit relatively lower expression levels of VDAC2 compared to normal tissues." (PMID 38732562, 2024). "The expression of VDAC2 was shown to increase in PAs with regrowth, which may suggest, as previously reported in other neoplasms, an antiapoptotic action of VDAC2 in PAs." (PMID 39449743, 2024). "Notably and unexpectedly, our results highlight an increased level of VDAC2 expression (an increased fold-change of 10.86 (p ≤ 0.05) when comparing tumor tissues between the excess iron vs. adequate iron groups), most likely in cells undergoing ferroptosis." (PMID 38732562, 2024). "VDAC2 has been shown to promote cell apoptosis and limit tumor development through BAX." (PMID 38881325, 2024).
tumor (continued). "Malonylation of VDAC2 may induce mitochondrial dysfunction, increase mitochondrial ROS levels, lead to cell iron death, and inhibit tumor development." (PMID 38881325, 2024). "VDAC2 was upregulated in tumor samples in TCGA and was correlated with advanced stages." (PMID 38382091, 2024). "The present study found that VDAC2 knockdown increased the resistance of cells to erastin‐induced iron death, suggesting that VDAC2 silencing could indeed increase cell resistance to iron death, therebt promoting tumor development." (PMID 38881325, 2024). "FADS2, PHKG2, and VDAC2 were significantly related to tumor invasion depth." (PMID 38743344, 2024). "These experiments indicated that VDAC2 silencing could increase the resistance of OC cells to iron death and that VDAC2 had the potential to inhibit tumor development." (PMID 38881325, 2024). "IHC staining of tumor and adjacent healthy tissues indicated up-regulation of the VDAC2, CSNK2A2, and MIF genes in tumor tissues, although the expression levels of ODC1 did not change, possibly because of the large differences in the positive signal values between the various samples." (PMID 37231440, 2023). "Overall, these data suggest that 2‐BP by inhibiting the ZDHHC/STING/VDAC2 signaling reduces tumor growth in RCC and may be a promising agent in treating patients with RCC." (PMID 36445063, 2023). "Particularly, VDAC2 was highly expressed in tumor tissues relative to normal tissues." (PMID 36274128, 2022). "Since the intrinsic apoptotic pathway is an important barrier to tumorigenesis, we hypothesized that the impairment of BAX-mediated apoptosis by deletion of Vdac2, when combined with Bak deletion, should accelerate tumor development." (PMID 30478310, 2018). "Moreover, the tumor formation ability of GBM2-GSCs was potently reduced by enforced VDAC2 expression." (PMID 30250190, 2018). "Furthermore, preventing Bak sequestration by VDAC2 or inducing Bak activation by dissociation from VDAC2 is considered a plausible approach to trigger apoptosis in tumor cells." (PMID 28713289, 2017). "The anti-tumor agent erastin was found to bind directly to VDAC2 and induce non-apoptotic cell death in some tumor cells that harbored activating mutations in the RAS–RAF–MEK pathway." (PMID 28824871, 2017). "Collectively, the aberrant expression of VDAC2 might show tumor promoting role in NSCLC." (PMID 38382091, 2024). "Since STING‐C91A/C88A mutant is deficient in binding VDAC2, and STING palmitoylation on both C91 and C88 were observed to maintain STING function on Golgi, we reasoned that inhibiting STING palmitoyltransferase(s) would be an approach to maximize tumor inhibition." (PMID 36445063, 2023). "However, in our patient samples, although VDAC2 was differentially expressed in tumour samples and was associated with RFS, no significance was observed in OS." (PMID 37496319, 2023). "Notably, genes associated with the glycolysis/gluconeogenesis pathway including LDHA —whose overexpression in cancer is associated with proliferation and malignancy— and several glycolytic genes (e.g. HK1, VDAC1, and VDAC2) were only upregulated in LB fHER2− tumours and derived CLs." (PMID 36220861, 2022). "Overall, these findings suggested that RRM2, SLC2A1, DDIT4, and VDAC2 were potential oncogene, whereas PEBP1 and IL33 were candidate tumor suppressor genes." (PMID 39311766, 2024). "In summary, our study reveals that the tumour cell-intrinsic E3 ligase TRIM21 inhibits radiation-initiated, VDAC2 dependent, and mtDNA-induced STING–type-I IFN signalling and antitumour immune responses in NPC." (PMID 36797289, 2023). "Four ferroptosis driver genes FLT3, ALOX12B, ALOX15, and VDAC2, had a low CNV, and four ferroptosis suppressor genes ACSL3, CISD1, FANCD2, and SLC3A2, had a high CNV, indicating that ferroptosis was inhibited in tumor development." (PMID 34434214, 2021).
tumor (continued). "Our preclinical study showed that enforced VDAC2 potently disrupted GSC glycolysis, mitigated GSC-driven tumor growth, and extended the survival of tumor-bearing mice." (PMID 30250190, 2018). "Here, the authors perform a genome-wide CRISPR/Cas9 screen and identify VDAC2 as a promoter of BAX-mediated apoptosis that is important for an efficient chemotherapeutic response and to suppress tumor formation." (PMID 30478310, 2018). "Nonetheless, interestingly, VDAC2 was overexpressed in tumors that regrew after surgery, regardless of the tumor subgroup." (PMID 39449743, 2024). "Briefly, the tumor (N = 7) and adjacent (N = 6) tissues of OS patients were collected and stained using IHC, showing that CSNK2A2, VDAC2, and MIF were markedly upregulated in OS tissues compared with the control tissues, whereas the expression of ODC1 showed no significant change." (PMID 37231440, 2023). "Binding of STING with VDAC2, ATP2A2, and ATP1A1 was confirmed in both A498 and RCC10 tumor cells." (PMID 36445063, 2023). "Given that our data implicates a central role for VDAC2 in promoting BAX-mediated apoptosis, we hypothesized that the BAX:VDAC2 interaction would also be important for the activity of BAX in tumor cells responding to chemotherapeutic agents." (PMID 30478310, 2018). "In addition, the expression of VDAC2 and IFNG were decreased in the tumor tissues." (PMID 34885178, 2021).
cancer (23 papers, 2012 to 2024). A tumor composed of atypical neoplastic, often pleomorphic cells that invade other tissues. "Further, expression of the voltage-gated channel VDAC2 is also associated with increased risk in some cancers." (PMID 38049632, 2023). "These actions of VDAC2 in regulating energy metabolism and mitochondria-associated apoptosis makes VDAC2 an interesting potential target for cancer treatment." (PMID 32641986, 2020). "Our findings indicated that VDAC2 knockdown increased cell resistance to iron death, suggesting that VDAC2 had the potential to promote apoptosis and subsequently inhibit cancer development." (PMID 38881325, 2024). "In the TCGA-LUAD dataset, we found that the VDAC2 was significantly highly expressed in cancer samples comparing to adjacent samples (cancer vs. normal)." (PMID 38382091, 2024). "The results reported in the literature regarding VDAC2 expression in malignant neoplasms are inconsistent." (PMID 39449743, 2024). "VDAC2–tubulin interaction and VDAC2–PFKP interaction have been studied in cancer metabolism research were specifically targeting VDAC2 has shown to down-regulate glycolysis thereby preventing cancer cell growth and proliferation." (PMID 34321484, 2021). "Depletion of Nedd4 limits the protein degradation of VDAC2/3, which increases the sensitivity of cancer cells to erastin." (PMID 31974380, 2020). "VDAC1 and VDAC2 isolated after VDAC2/3 or VDAC1/3 double knockdown in cancer cells were shown to be sensitive to tubulin inhibition." (PMID 30542671, 2017). "A second group of proteins associated with metabolism and apoptosis, including VDAC1, VDAC2 and AIF, were reported for some cancers other than CLL (group B)." (PMID 27078856, 2016). "Erastin reprograms cancer cell metabolism by modulating VDAC2/VDAC3 and system xc- to trigger ferroptosis." (PMID 26405158, 2015). "Excessive activation of the Ras-MEK pathway may enhance ROS generation by inhibiting Cys2 uptake or VDAC2/3 in mitochondria, thereby sensitizing cancer cells to ferroptosis." (PMID 39532842, 2024). "VDAC2 is also a target of erastin, a small-molecule promotor of ferroptosis in cancer cells." (PMID 38049632, 2023). "Thus, this VDAC2–BAK interaction site can potentially be targeted to either inhibit BAK-mediated apoptosis in scenarios where excessive apoptosis contributes to disease or to promote BAK-mediated apoptosis for cancer therapy." (PMID 38696533, 2024). "In addition, rescue experiments showed that VDAC2 could reduce the cancer‐promoting effect induced by TRIM8." (PMID 38881325, 2024). "Erastin‐VDAC2 interaction inhibits the permeability of VDAC2 to endogenous substrates, such as NADH and decrease the NADH oxidation in cancer cells, which induces mitochondrial dysfunction and the release of oxidative species." (PMID 31232522, 2019). "In cancer cells, high free tubulin inhibits VDAC1 and VDAC2, contributing to suppression of mitochondrial function in the Warburg phenomenon." (PMID 29312883, 2017). "Despite this important function in apoptosis, while interactions with pro-survival family members are well characterised and have culminated in the development of drugs that target these interfaces to induce cancer cell apoptosis, the interaction between BAK and VDAC2 remains largely undefined." (PMID 38696533, 2024). "The isoforms of VDAC2 and VDAC3 are involved in erastin-mediated ferroptosis (cancer)." (PMID 38515787, 2024). "For example, BAX-mediated killing of cancer cells by venetoclax was abrogated in the absence of VDAC2." (PMID 30478310, 2018).
infection (5 papers, 2007 to 2024). The state of being infected such as from the introduction of a foreign agent such as serum, vaccine, antigenic substance or organism. "Intriguingly, although Ctr-infection was able also to protect VDAC2-deficient cells against apoptosis induced by ABT-737/S63845, this protection was clearly reduced compared to wt HeLa cells." (PMID 35397654, 2022). "Reconstitution of VDAC2-deficient cells with VDAC2 restored the protection by Ctr-infection." (PMID 35397654, 2022). "The mitochondrial proteins VDAC2 and cytochrome bc1 found in abundance in NiV-infected human neuronal cells, on the other hand, are two proteins that could be associated with the induction of apoptosis and cellular pathologic response to the infection." (PMID 17553172, 2007). "The significant downregulation of genes like Stat3 and Vdac2, key mediators in necroptosis, points to a viral strategy to inhibit cell death that would otherwise limit infection spread." (PMID 39364165, 2024). "The quantification of VDAC2 mRNA showed a transient upregulation in early stages of infection, while notable downregulation occurred at later stages of infection." (PMID 37515204, 2023). "OmpA alone blocked apoptosis and reproduced the changes to Bak-activation observed during infection, reminiscent of the activity of VDAC2." (PMID 35397654, 2022). "The only known human protein that could perhaps explain the observed inhibition of Bax and Bak during Ctr-infection is the already mentioned porin VDAC2." (PMID 35397654, 2022). "Infection further inhibited apoptosis induced conformational changes of Bak, as evidenced by changes to protease sensitivity, oligomerization and release from the mitochondrial porin VDAC2." (PMID 35397654, 2022). "LCDV-, VDAC2-, and RACK1-positive green signals were also widely distributed at 2 h post-infection; the merging of CTB images with LCDV, VDAC2, and RACK1 images revealed many yellow co-localization signals in the cell membrane and cytoplasm." (PMID 32630682, 2020). "Infection with hRSV ON1 resulted in downregulation of the Mfn1, VDAC2, and PINK1 mRNAs." (PMID 37515204, 2023). "suggest that the downregulation of VDAC2, Mfn1, and PINK might be an antiviral response that limits the progression of the infection and therefore at these time points most mitochondria have normal morphology." (PMID 37515204, 2023). "The mRNA-levels of VDAC2 were not significantly altered in a study measuring global gene expression during Ctr-infection." (PMID 35397654, 2022). "However, the protective effect of Ctr-infection was reduced in cells lacking the Bax/Bak-regulator VDAC2." (PMID 35397654, 2022).
adenocarcinoma (1 paper, 2014). A common cancer characterized by the presence of malignant glandular cells. "Interestingly, the three genes (VDAC1, VDAC2, and VDAC3,) coding for voltage-dependent anion channels (VDACs), which is a class of porin ion channel located on the outer mitochondrial membrane, were all down-regulated in adenocarcinoma." (PMID 24466154, 2014).
VDAC2 also shares sentences with these, for which no sentence is quoted: diabetes (3 papers); Alzheimer disease (2); cardiac arrhythmia (2); glaucoma (2); infertile (2); neurodevelopmental disorder (2); amyotrophic lateral sclerosis (1); B-cell NHL (1); brain disease (1); colorectal tumors (1); cyst (1); diabetic cardiomyopathy (1); frontotemporal dementia (1); heart disease (1); idiopathic dilated cardiomyopathy (1); Intellectual disability (1); leukemia (1); male fertility (1); myocardial ischemia (1); neurodegenerative disease (1); paraganglioma (1); pheochromocytoma (1); prion disease (1); renal cell carcinoma (1).